SYAP1 (synapse associated protein 1)
Description:
Plays a role in adipocyte differentiation by promoting mTORC2-mediated phosphorylation of AKT1 at 'Ser-473' after growth factor stimulation.
Synonyms: BSTA; PRO3113; FLJ14495; SAP47
Tractability: Antibody: UniProt places it where antibodies can reach, with medium confidence; its Gene Ontology location is reachable by antibodies, with medium confidence. PROTAC: ubiquitination databases record sites on it; its protein half-life has been measured.
Gene: Protein-coding gene on chromosome X (16,719,545 to 16,765,340, forward strand). Ensembl gene ENSG00000169895.
Subcellular location: Cytoplasm, perinuclear region; Golgi apparatus; Perikaryon; Cell projection, axon; Cell projection, dendrite; Cell projection, growth cone; Presynaptic cell membrane; Postsynaptic cell membrane; Membrane
Subcellular location (Human Protein Atlas): Golgi apparatus; Cytosol; Nucleoplasm
Gene Ontology:
Molecular function: protein binding
Biological process: cellular response to epidermal growth factor stimulus; cellular response to insulin stimulus; cellular response to insulin-like growth factor stimulus; cellular response to platelet-derived growth factor stimulus; positive regulation of fat cell differentiation; positive regulation of protein serine/threonine kinase activity; TORC2 signaling; regulation of short-term neuronal synaptic plasticity
Cellular component: cytoplasmic side of plasma membrane; cytosol; extracellular exosome; Golgi apparatus; membrane; nucleoplasm; axon; cytoplasm; dendrite; growth cone; nucleus; perikaryon; perinuclear region of cytoplasm; postsynaptic membrane; presynaptic membrane; synapse
Homologues: Orthologues: macaque SYAP1 (99% identical), pig SYAP1 (92% identical), rabbit SYAP1 (91% identical), dog SYAP1 (90% identical), guinea pig SYAP1 (87% identical), rat Syap1 (86% identical), mouse Syap1 (84% identical), tropical clawed frog syap1 (72% identical), chimpanzee SYAP1 (69% identical), zebrafish syap1 (65% identical), Drosophila melanogaster Sap47 (36% identical), Caenorhabditis elegans C16C2.4 (30% identical). Paralogues in human: BSDC1 (19% identical).
Diseases named in the same sentence as SYAP1 in open-access papers:
SYAP1 is named in the same sentence as 13 diseases in open-access papers, as found by Europe PMC text mining. Sharing a sentence is not in itself a finding about the gene and the disease. The quoted sentences say what the papers report.
mental retardation (3 papers, 2019 to 2024). "The human gene encoding SYAP1 is located within chromosomal band Xp22.2, a region associated with mental retardation, developmental delay, and autism spectrum disorder." (PMID 38764741, 2024). "Syap1-deficient mice have been shown to display motor and movement defects; Ap1s2 has been associated with intellectual disability, basal ganglia disease, and seizures accompanying Pettigrew syndrome." (PMID 34034791, 2021). "The human gene encoding the synapse-associated protein 1 (SYAP1) is located within chromosomal band Xp22.2, a region associated with mental retardation, developmental delay and autism spectrum disorder." (PMID 31118165, 2019).
autism spectrum disorder (2 papers, 2019 to 2024). A spectrum of developmental disorders that includes autism, and Asperger syndrome. "In two human patients with autism spectrum disorder, copy number variants affecting the SYAP1 gene have been observed." (PMID 31118165, 2019).
glioma (1 paper, 2022). A benign or malignant brain and spinal cord tumor that arises from glial cells (astrocytes, oligodendrocytes, ependymal cells). "Mutations in XIE genes USP9X, NLGN4x, PLXNB3 (involved in axonal guidance and glioma invasion), SYAP1, SRPX2, and ZFX (ZFX-SMARCA1 fusion) occurred in non-MN1-BEND2, predominantly female cases." (PMID 35440587, 2022).
tumor (1 paper, 2023). "Utilizing the GEPIA database, SYAP1 was found to be significantly expressed in tumor tissues in the majority of malignancies when examining the relative expression of SYAP1 in pan-cancerous tumors and adjacent tumors and LUAD patients with high SYAP1 expression have poorer OS." (PMID 37256127, 2023).
SYAP1 also shares sentences with these, for which no sentence is quoted: infection (8 papers); cancer (2); developmental delay (2); adenocarcinoma (1); amnesia (1); Anxiety (1); autism (1); bone disorder (1); Pettigrew syndrome (1).